CNOT1 (CCR4-NOT transcription complex subunit 1)
Description:
Scaffolding component of the CCR4-NOT complex which is one of the major cellular mRNA deadenylases and is linked to various cellular processes including bulk mRNA degradation, miRNA-mediated repression, translational repression during translational initiation and general transcription regulation. Additional complex functions may be a consequence of its influence on mRNA expression. Its scaffolding function implies its interaction with the catalytic complex module and diverse RNA-binding proteins mediating the complex recruitment to selected mRNA 3'UTRs. Involved in degradation of AU-rich element (ARE)- containing mRNAs probably via association with ZFP36. Mediates the recruitment of the CCR4-NOT complex to miRNA targets and to the RISC complex via association with TNRC6A, TNRC6B or TNRC6C. Acts as a transcriptional repressor. Represses the ligand-dependent transcriptional activation by nuclear receptors. Involved in the maintenance of embryonic stem (ES) cell identity. Plays a role in rapid sperm motility via mediating timely mRNA turnover (By similarity).
Synonyms: NOT1H; CDC39; KIAA1007; NOT1; AD-005; HPE12; VIBOS
Tractability: Small molecule: a structure with a bound ligand is known. PROTAC: ubiquitination databases record sites on it; its protein half-life has been measured.
Gene: Protein-coding gene on chromosome 16 (58,519,951 to 58,629,885, reverse strand). Ensembl gene ENSG00000125107.
Subcellular location: Cytoplasm, P-body; Nucleus
Subcellular location (Human Protein Atlas): Cytosol
Pathways (Reactome):
Developmental Biology: M-decay: degradation of maternal mRNAs by maternally stored factors
Metabolism of RNA: Deadenylation of mRNA
Gene Ontology:
Molecular function: armadillo repeat domain binding; molecular adaptor activity; nuclear estrogen receptor binding; nuclear retinoic acid receptor binding; poly(A)-specific ribonuclease activity; protein binding; protein domain specific binding; RNA binding
Biological process: miRNA-mediated post-transcriptional gene silencing; negative regulation of intracellular estrogen receptor signaling pathway; negative regulation of retinoic acid receptor signaling pathway; negative regulation of transcription by RNA polymerase II; negative regulation of translation; positive regulation of cytoplasmic mRNA processing body assembly; positive regulation of mRNA catabolic process; positive regulation of nuclear-transcribed mRNA catabolic process, deadenylation-dependent decay; positive regulation of nuclear-transcribed mRNA poly(A) tail shortening; regulation of stem cell population maintenance; nuclear-transcribed mRNA catabolic process, deadenylation-dependent decay; nuclear-transcribed mRNA poly(A) tail shortening; trophectodermal cell differentiation
Cellular component: CCR4-NOT complex; extracellular region; membrane; P-body; CCR4-NOT core complex; cytosol; nucleus
Genetic constraint (gnomAD): Loss-of-function variants: 10 observed, 265.71 expected, observed/expected ratio (o/e) 0.0376, 90% interval 0.022 to 0.064. The upper end of that interval is the gene's LOEUF score, 0.064, which puts it in group 1 of 6, group 1 being the genes least tolerant of losing a copy. Missense variants: 1,570 observed, 2,927.6 expected, observed/expected ratio (o/e) 0.54, 90% interval 0.51 to 0.56. Synonymous variants: 980 observed, 1,020.2 expected, observed/expected ratio (o/e) 0.96, 90% interval 0.91 to 1.01.
Gene-disease validity (ClinGen):
ClinGen rates the evidence that CNOT1 causes each of these diseases.
complex neurodevelopmental disorder (autosomal dominant): Definitive. A disorder that involves more than one phenotype associated with the central nervous system, including but not limited to intellectual disability, autism, and seizures (epilepsy).
holoprosencephaly 12 with or without pancreatic agenesis (autosomal dominant): Limited.
Homologues: Orthologues: chimpanzee CNOT1 (100% identical), macaque CNOT1 (99% identical), rabbit CNOT1 (99% identical), mouse Cnot1 (99% identical), rat Cnot1 (99% identical), dog CNOT1 (98% identical), pig CNOT1 (98% identical), guinea pig CNOT1 (95% identical), tropical clawed frog cnot1 (94% identical), zebrafish cnot1 (91% identical), Drosophila melanogaster Not1 (49% identical), Caenorhabditis elegans let-711 (37% identical).
Diseases named in the same sentence as CNOT1 in open-access papers:
CNOT1 is named in the same sentence as 48 diseases in open-access papers, as found by Europe PMC text mining. Sharing a sentence is not in itself a finding about the gene and the disease. The quoted sentences say what the papers report.
holoprosencephaly (5 papers, 2019 to 2025). Holoprosencephaly (HPE) is a complex brain malformation resulting from incomplete cleavage of the prosencephalon, occurring between the 18th and 28th day of gestation, and affecting both the forebrain and face, which results in neurological manifestations and facial anomalies of variable severity. "Monoallelic missense CNOT1 variants have been associated with holoprosencephaly-12 with pancreatic agenesis (OMIM #619033)." (PMID 41155467, 2025). "For instance, the mutations in CNOT1 are related to syndrome of pancreatic agenesis and holoprosencephaly (HPE)." (PMID 35390160, 2022). "CNOT1, a transcriptional repressor, is crucial for maintaining embryonic stem cells in a pluripotent state, and a specific CNOT1 mutation can lead to holoprosencephaly and the novel syndrome of pancreatic agenesis." (PMID 33232269, 2020). "In addition, it has been reported that two unrelated individuals with semilobar holoprosencephaly (the incomplete separation of the forebrain during embryogenesis) have identical missense variants in the CNOT1 gene." (PMID 33138308, 2020). "The pancreatic and neurological phenotypes observed in Cnot1p.(Arg535Cys)/p.(Arg535Cys) E14.5 mouse embryos are consistent with the pancreatic agenesis and holoprosencephaly observed in the three case subjects, confirming that the de novo CNOT1 mutation is indeed the cause of their disease." (PMID 31006513, 2019). "Our study identifies a spontaneous CNOT1 p.Arg535Cys mutation as the genetic cause of a rare syndrome of pancreatic agenesis and holoprosencephaly, highlighting a previously unsuspected role of CNOT1 as a key factor in both pancreatic and neurological development." (PMID 31006513, 2019).
osteosarcoma (5 papers, 2017 to 2023). A usually aggressive malignant bone-forming mesenchymal neoplasm, predominantly affecting adolescents and young adults. "In order to determine the underlying mechanism of CNOT1 in osteosarcoma, Co‐IP followed by mass spectrometry identification was performed in MNNG/HOS cells." (PMID 28188704, 2017). "Moreover, the lamin A-dependent CNOT1 level was positively associated with the Enneking stage and tumour recurrence of patients with osteosarcoma by activation of the Hh/Gli pathway, and CNOT1 works as an oncogene in osteosarcoma development." (PMID 29899399, 2018). "Notably, the CNOT1 expression was significantly associated with tumor recurrence, Enneking stage, and poor survival in patients with osteosarcoma." (PMID 28188704, 2017). "The low expression of CNOT1 increases the overall rate of survival (generated using the Kaplan–Meier method) in gastric cancer and osteosarcoma." (PMID 37508532, 2023). "prove that CNOT1 cooperates with LMNA to aggravate the occurrence of osteosarcoma by regulating the Hedgehog signaling pathway." (PMID 37377953, 2023). "Significantly, CNOT1 interacts with LMNA (lamin A) in osteosarcoma cells and depletion of CNOT1 suppresses the cell proliferation through the Hedgehog signaling pathway via its association with LMNA." (PMID 33138308, 2020). "This is consistent with flow cytometric analysis which has revealed that depletion of CNOT1 delays cell cycle progression by inhibiting S phase transition in osteosarcoma cells." (PMID 33138308, 2020). "The mRNA and protein expression of CNOT1 significantly decreased after transfection with CNOT1‐specific siRNA in osteosarcoma cells." (PMID 28188704, 2017). "Further analysis indicated that CNOT1 levels were correlated positively with recurrence (P = 0.005), indicating that CNOT1 expression played an important role in osteosarcoma recurrence." (PMID 28188704, 2017). "The results showed that CNOT1 specifically interacted with LMNA in osteosarcoma cells as indicated by the Co‐IP assay." (PMID 28188704, 2017). "This study, for the first time, demonstrates the interaction of CNOT1 with LMNA in osteosarcoma cells." (PMID 28188704, 2017). "To further determine the clinicopathologic significance of CNOT1 in osteosarcoma, we performed IHC analysis of CNOT1 in a tissue microarray that included an independent set of 151 cases of osteosarcoma." (PMID 28188704, 2017). "In summary, CNOT1 was correlated with LMNA in tumor samples and associated with poor prognosis in patients with osteosarcoma." (PMID 28188704, 2017). "A rescue study showed that the decreased growth of osteosarcoma cells and inhibition of the Hedgehog signaling pathway by CNOT1 depletion were reversed by LMNA overexpression, indicating that the activity of CNOT1 was LMNA dependent." (PMID 28188704, 2017). "Collectively, knockdown of CNOT1 dramatically inhibits osteosarcoma cell growth in vitro and in vivo." (PMID 28188704, 2017). "To date, the mechanisms and regulatory roles of CNOT1 in tumors, including osteosarcoma, remain largely elusive." (PMID 28188704, 2017). "Taken together, knockdown of CNOT1 inhibited osteosarcoma growth through the Hedgehog signaling pathway via its association with LMNA, suggesting a candidate orientation for osteosarcoma treatment." (PMID 28188704, 2017). "The results showed that knockdown of CNOT1 dramatically inhibited osteosarcoma cell proliferation in MNNG/HOS cells." (PMID 28188704, 2017). "Here, we present evidence that knockdown of CNOT1 inhibits the growth of osteosarcoma in vitro and in vivo." (PMID 28188704, 2017). "CCK‐8 assay revealed that knockdown of CNOT1 significantly inhibited the proliferation of osteosarcoma cells." (PMID 28188704, 2017). "This study demonstrated that knockdown of CNOT1 inhibited osteosarcoma cell growth in vitro and in vivo." (PMID 28188704, 2017). "In the present study, we found that knockdown of CNOT1 resulted in significant cell growth inhibition in osteosarcoma cells in vitro." (PMID 28188704, 2017).
osteosarcoma (continued). "Taken together, knockdown of CNOT1 inhibits osteosarcoma cell proliferation by inhibition of the Hedgehog signaling pathway via LMNA." (PMID 28188704, 2017). "The RNA‐seq analysis revealed that CNOT1 depletion inhibited the Hedgehog signaling pathway in osteosarcoma cells." (PMID 28188704, 2017). "Functional screening was conducted, and the results showed that knockdown of CNOT1 significantly inhibited osteosarcoma cell proliferation, suggesting an important role of CNOT1 in osteosarcoma carcinogenesis." (PMID 28188704, 2017). "Taken together, these results indicated that CNOT1 knockdown hindered the tumorigenesis of osteosarcoma cells in vivo." (PMID 28188704, 2017). "Taken together, these results suggest that the CNOT1–LMNA–Hedgehog signaling pathway axis exerts an oncogenic role in osteosarcoma progression, which could be a potential target for gene therapy." (PMID 28188704, 2017). "Knockdown of CNOT1 affected the protein expression level of LMNA in osteosarcoma cells." (PMID 28188704, 2017). "Similarly, we also confirmed the colocalization of LMNA and CNOT1 in osteosarcoma cells by confocal analysis." (PMID 28188704, 2017). "Therefore, knockdown of CNOT1 inhibits the Hedgehog signaling pathway in osteosarcoma." (PMID 28188704, 2017). "Taken together, these results strengthen the conclusion that CNOT1 interacts with LMNA and functions as a positive regulator of LMNA protein in osteosarcoma." (PMID 28188704, 2017). "More importantly, this report provides, for the first time, experimental evidence and implicates the significance of the interaction between CNOT1 and LMNA in osteosarcoma cells." (PMID 28188704, 2017). "In the present study, we found that CNOT1 and LMNA interacted with each other in osteosarcoma cells." (PMID 28188704, 2017). "The results showed that knockdown of CNOT1 significantly inhibited the expression of GLI1, PTCH1, and PTCH2 in osteosarcoma cells." (PMID 28188704, 2017). "Our data demonstrated that CNOT1 interacted with LMNA and affected its protein stability in osteosarcoma cells." (PMID 28188704, 2017). "CCR4-NOT transcription complex subunit 1 (CNOT1) was correlated with the cell growth of osteosarcoma cells via clinical screening and functional evaluation." (PMID 29899399, 2018). "In addition, CNOT1 was found to interact with lamin A (LMNA) and affect its protein stability in osteosarcoma." (PMID 28188704, 2017). "Notably, we found that CNOT1 was an independent prognostic factor for tumor‐free survival (TFS) and OS in patients with osteosarcoma." (PMID 28188704, 2017). "Through clinical screening and functional evaluation, CCR4–NOT transcription complex subunit 1 (CNOT1) correlated with the growth of osteosarcoma cells." (PMID 28188704, 2017). "The results showed that CNOT1, ASNS, and EFHD2 were overexpressed in osteosarcoma tissues compared with normal tissues, suggesting that they might play an important role in the tumorigenesis of osteosarcoma." (PMID 28188704, 2017). "Therefore, interventions targeting the CNOT1–LMNA–Hedgehog signaling pathway axis may be a feasible and effective strategy for the treatment of osteosarcoma." (PMID 28188704, 2017). "Through clinical analysis and functional screening, CNOT1, a member of the human CCR4–NOT deadenylase complex, was found to be related to osteosarcoma proliferation." (PMID 28188704, 2017).
breast carcinoma (3 papers, 2016 to 2022). "In triple-negative breast cancer, IGF2BP3 and IGF2BP2 synergistically recruited CNOT1 complex, reduced the stability of progesterone receptor and ultimately promoted the migration and metastasis of breast cancer." (PMID 35676262, 2022).
liver cancer (3 papers, 2018 to 2025). An epithelial or non-epithelial malignant neoplasm that arises from the liver. "Finally, the RBP IGF2BP1 (IGF2 mRNA-binding protein-1) destabilizes the liver-cancer-associated lncRNA HULC (Highly Upregulated in Liver Cancer) in a CNOT1-dependent manner." (PMID 39941720, 2025). "Interestingly, the upregulation of the histone deacetylases 1 and 3 (HDAC1/3) promotes the overexpression of CNOT1 in hepatic cancer cells." (PMID 39941720, 2025).
lung carcinoma (3 papers, 2017 to 2023). "The possibility that p21 is targeted by Ccr4a/b is supported by previous observations that p21 can be stabilized by depletion of CNOT1 in mouse embryonic fibroblasts or CNOT3 in A549 lung cancer cells." (PMID 33671234, 2021). "We found that CNOT1 expression also correlated negatively with patient OS in lung cancer and gastric cancer." (PMID 28188704, 2017).
pancreatic agenesis (3 papers, 2019 to 2025). Partial agenesis of the pancreas is characterized by the congenital absence of a critical mass of pancreatic tissue. "We identified a heterozygous missense mutation in CNOT1 (MIM: 604917; GenBank: NM_016284.4; c.1603C>T [p.Arg535Cys]) in three individuals with pancreatic agenesis." (PMID 31006513, 2019).
adenovirus infection (1 paper, 2018). "The levels of at least 2 other members of the complex (CNOT3 and CNOT7) are also reduced during adenovirus infection, whereas the levels of CNOT4 and CNOT1 remain stable." (PMID 29593045, 2018).
Arrhythmia (1 paper, 2020). Any cardiac rhythm other than the normal sinus rhythm. "Furthermore, the cardiac-specific knockdown of Drosophila orthologs of CCR4-NOT genes in vivo (CNOT1/Not1 and CNOT7/8/Pop2) was either lethal or resulted in dilated cardiomyopathy, reduced contractility or a propensity for arrhythmia." (PMID 32471864, 2020).
development (1 paper, 2023). "CLEC16A and CNOT1 code for autophagy- and RNA turnover-related factors, and their dysregulations are associated with Parkinson's disease and impaired neurological development, respectively." (PMID 37026480, 2023).
developmental delay (1 paper, 2025). "The clinical presentation of our second case, MN90, predominantly shows signs of motor and speech developmental delay, seizures, ID, ASD, and behavioral problems, in association with a heterozygous truncating variant in the CNOT1 gene (OMIM #604917), classified as likely pathogenic." (PMID 41155467, 2025).
diabetes (1 paper, 2025). "Through the analysis involving differential gene expression and machine learning-based feature selection, we identified a subset of key genes, including CNOT1, KRT73, and CLEC2D, which consistently emerged across multiple models as potential biomarkers for early diabetes prediction." (PMID 40740938, 2025).
Fulminant hepatitis (1 paper, 2020). Acute hepatitis complicated by acute liver failure with hepatic encephalopathy occurring less than 8 weeks after the onset of jaundice. "Thus, Cnot1-LKO mice could be added to hepatitis models to help develop therapeutics for fulminant hepatitis." (PMID 32238456, 2020).
Glucose intolerance (1 paper, 2019). Glucose intolerance (GI) can be defined as dysglycemia that comprises both prediabetes and diabetes. "Indeed, Cnot1-AKO mice showed hyperinsulinemia, hyperglycemia, insulin resistance, and glucose intolerance and they could not maintain a normal body temperature during cold exposure." (PMID 31652943, 2019).
HCMV infection (1 paper, 2023). "During infection of CNOT1‐depleted cells, we detected impaired progression though the viral lifecycle, extension of host mRNA poly(A)‐tails, and changes to the expression of host factors previously implicated in the regulation of HCMV infection." (PMID 37846490, 2023). "Correspondingly, the effect of CNOT1 depletion on viral protein accumulation followed identical kinetics in TB40/E (Fig EV2E) compared to AD169 HCMV infection and released viral titers following a low MOI TB40/E infection were reduced by more than 104‐fold (Fig EV2F)." (PMID 37846490, 2023).
Hepatitis (1 paper, 2020). Inflammation of the liver. "Consequently, disruption of the CCR4–NOT function through CNOT1 depletion induces aberrant gene expression that is associated with lethal hepatitis." (PMID 32238456, 2020).
Hyperinsulinemia (1 paper, 2019). An increased concentration of insulin in the blood. "Cnot1-AKO mice showed hyperinsulinemia, which might partly explain the normal or slightly enhanced glucose metabolism." (PMID 31652943, 2019).
Intellectual disability (1 paper, 2022). "Moreover, individuals with mutations in CNOT1 exhibit a broad range of neurodevelopmental phenotypes, most consistently resulting in intellectual disability, development, speech, and motor delay, and hypotonia." (PMID 35357307, 2022).
leukemia (1 paper, 2024). A malignant (clonal) hematologic disorder, involving hematopoietic stem cells and characterized by the presence of primitive or atypical myeloid or lymphoid cells in the bone marrow and the blood. "In our study, we observed minimal impact on CNOT1 protein abundance, at least at the early time points when CNOT3 was depleted in leukemia cells and HSPCs." (PMID 38491013, 2024).